MIR486-2 (microRNA 486-2)
Synonyms: hsa-mir-486-2; mir-486-2
Gene: MicroRNA gene on chromosome 8 (41,660,444 to 41,660,507, forward strand). Ensembl gene ENSG00000283450.
Gene Ontology:
Biological process: miRNA-mediated post-transcriptional gene silencing
Cellular component: RISC complex